C17orf78 (chromosome 17 open reading frame 78)
Synonyms: FLJ39647
Tractability: Antibody: UniProt predicts a signal peptide or a membrane-spanning region.
Gene: Protein-coding gene on chromosome 17 (37,375,985 to 37,392,708, forward strand). Ensembl gene ENSG00000278505.
Subcellular location: Membrane
Gene Ontology:
Cellular component: membrane
Genetic constraint (gnomAD): Loss-of-function variants: 26 observed, 24.21 expected, observed/expected ratio (o/e) 1.07, 90% interval 0.79 to 1.49. The upper end of that interval is the gene's LOEUF score, 1.49, which puts it in group 6 of 6, group 1 being the genes least tolerant of losing a copy. Missense variants: 207 observed, 261.72 expected, observed/expected ratio (o/e) 0.79, 90% interval 0.7 to 0.89. Synonymous variants: 89 observed, 94.61 expected, observed/expected ratio (o/e) 0.94, 90% interval 0.79 to 1.12.
Homologues: Orthologues: chimpanzee C17H17orf78 (98% identical), macaque C16H17orf78 (92% identical), pig C17orf78 (73% identical), rat C10h17orf78 (65% identical), mouse Gm11437 (63% identical), dog C9H17orf78 (37% identical).